LDHB (lactate dehydrogenase B)
Diseases named in the same sentence as LDHB in open-access papers (continued):
Sharing a sentence is not in itself a finding about the gene and the disease.
tumor (continued). "Indeed, we also observed that tumor initiation was dramatically reduced but not completely abrogated, both in xenografts of A549 shLDHB clones and also in LDHB knockout animals." (PMID 35877003, 2022). "Notably, neither LDHA (p.adj=0.9869) nor LDHB (p.adj=0.9953) expression correlated with sLDH status, indicating that tumor cell expression of these genes did not explain differences in sLDH levels." (PMID 33016647, 2020). "LDHB in tumor cells utilize lactate as energy source by converting it to pyruvate, which feeds into the TCA cycle, indicating that the ECT of cells may also inhibit the reverse Warburg effect by downregulating LDHB expression." (PMID 31558821, 2019). "The significance of the LDHB role in tumor cell death, including apoptosis, is not well understood." (PMID 31035592, 2019). "Therefore, a significant difference in LDHA and LDHB expression levels with a predominance of LDHA expression i.e., in MDA−MB-231 adenocarcinoma cells, and LDHB in adenocarcinoma MCF-7 cells, can be observed in cells from the same spontaneous tumors or tumor cell lines." (PMID 31035592, 2019). "The dependency of embryonal‐like HB tumor cells on hexokinase 1, as well as the GLUT3, LDHB, and G6PC staining on tumor sections could be used as novel biomarkers to highlight metabolic variation in HB and guide future therapies based on metabolic vulnerabilities." (PMID 28923827, 2017). "Similarly, LDHB (p = 0.023) and PNN (p = 0.0.44) were significantly associated with grade of the tumor (data not shown)." (PMID 27802291, 2016). "However, the significance of LDHB in tumor progression and therapeutic outcomes remains elusive and not well characterized." (PMID 25973606, 2015). "Surprisingly, we found an overexpression of the lactate dehydrogenase B enzyme in certain cancers and no significant upregulation of the lactate dehydrogenase A enzyme that has been suggested to have a ubiquitous role in tumor metabolism and growth." (PMID 25243088, 2014). "Indeed, LDHB expression did not affect the tumor growth in immunodeficient nude mice." (PMID 38739169, 2024). "Indeed, tumor tissues had higher levels of hypermethylation of the LDHB promoter than non-tumor." (PMID 38739169, 2024). "In comparison with peri-tumor tissues, most of the 24 cancer types in TCGA had overexpressed mRNA levels of LDHA, but not LDHB." (PMID 35637958, 2022). "LDHB expression does not have a pattern like LDHA, it can vary depending on the tumor type and the tumor’s dependence on aerobic glycolysis." (PMID 33668689, 2021). "Finally, we found that overexpression of LDHB suppressed HCC growth in immunocompetent but not in immunodeficient mice, suggesting that the host immune system was involved in the LDHB-medicated tumor suppression." (PMID 38739169, 2024). "Among most of these tumor types, a negative correlation between gene methylation and mRNA expression was revealed by calculating the Spearman correlation, including HIF1A, SLC16A1, UEVLD, SLC16A8, PFKFB2, LDHB, and SLC16A3." (PMID 37122693, 2023). "In addition to the absence of the enzymes LDHA and LDHB (LDH−/−), the LDH activity was significantly reduced in both LDH−/− tumor cell lines, although the expression of the lactate transporter MCT1 remained unaffected by the CRISPR/Cas9-induced LDHA/B double knockout." (PMID 34359663, 2021).
cancer (166 papers, 2010 to 2025). A tumor composed of atypical neoplastic, often pleomorphic cells that invade other tissues. "Here we show that LDHB protects cancer cells from mitochondria-associated ferroptosis via CoQ-dependent lactate oxidation, independently of lactate’s role as a carbon source." (PMID 40090955, 2025). "A critical mechanism underlying LDHB’s role in cancer progression involves its regulation of lysosomal function and autophagy." (PMID 40733189, 2025). "High tumoral LDHA/LDHB expression and lactate concentration are associated with cancer progression and poor prognosis in several cancers." (PMID 39796781, 2025). "In conclusion, our in vitro experiments showed that RT results in extensive mitochondrial lipid peroxidation, which LDHB silencing can further enhance, revealing that LDHB protects cancer cells from RT-induced mitochondria-associated ferroptosis." (PMID 40090955, 2025). "The bulk of lactate production within tumors is the result of lactate dehydrogenase (LDHA/LDHB) from the two most populous tumor cell types—cancer cells and cancer-associated fibroblasts (CAFs)." (PMID 39796781, 2025). "LDHB silencing alters mitochondrial morphology, causes lipid peroxidation, and reduces cancer cell viability, which is potentiated by the ferroptosis inducer RSL3." (PMID 40090955, 2025). "Here, the authors identify that LDHB protects cancer cells from mitochondria-associated ferroptosis via ubiquinol-dependent lactate oxidation, which is independent of lactate’s role as a carbon source." (PMID 40090955, 2025). "Given that GPER in CAFs enhances glutamine uptake in cancer cells by regulating LDHB expression, the underlying molecular mechanism of LDHB‐regulated lactate on glutamine absorption was investigated." (PMID 39690134, 2024). "Compared to the significant carcinogenic effect of LDHA in most cancers, the association between LDHB and tumors is much more complex." (PMID 38764020, 2024). "LDHB downregulation has been observed in various types of cancer, and it is important to understand the underlying mechanisms behind this phenomenon." (PMID 37547725, 2023). "PFKM expression levels have also been associated with cancer development and metastasis, LDHB catalyzes the interconversion of pyruvate and lactate." (PMID 37601754, 2023). "LDHB is associated with an aggressive cancer phenotype, and there are studies aimed at identifying and clinically applying selective inhibitors for LDHB." (PMID 37915411, 2023). "FGFR1-mediated metabolic LDHA activation and LDHB deactivation are associated with cancer growth and progression." (PMID 36077431, 2022). "FGF signaling also protects from LDHA degradation and deletion of FGFR1 blocks to use lactate as a main energy source and LDHB expression is associated with poor survival in cancer patients." (PMID 36077431, 2022). "AXKO-0046 and its derivatives can be used to validate LDHB-associated pathways in cancer metabolism." (PMID 34725423, 2021). "These investigators noted that a low LDHB/LDBA ratio was associated with enhanced glycolytic gene expression in cancer cells." (PMID 33400855, 2021). "Despite the suggested association between LDHB and cancer metabolism, LDHB-selective inhibitors remain unexplored." (PMID 34725423, 2021). "We analyzed tissue lactate concentration, LDH activity, and isozyme pattern, and LDHA/LDHB protein expression and localization in cancer-associated adipose tissue, compared to the breast adipose tissue of women with benign breast changes." (PMID 33353120, 2020). "Different cancers such as prostate, breast (ductal carcinoma in situ) and pancreatic cancers show suppressed or loss of LDHB expression as a crucial and early event in cancer development and progression." (PMID 31146503, 2019).
cancer (continued). "LDHB suppression also causes mitochondrial respiratory defects and plays role in cancer cell invasiveness by inducing the tight junction protein claudin-1 (CLN-1)." (PMID 31146503, 2019). "Exact mechanism through which LDHB contributes to cancer development and progression is not fully understood but changes in LDHB expression are often associated with early metabolic adaptations." (PMID 31146503, 2019). "It has been reported that reduced expression of LDHB is associated with progression of PCa and other forms of cancer." (PMID 31316912, 2019). "Moreover, low level of LDHB expression was associated with enhanced cancer cell glycolysis and lactate release as well as poor prognosis of HCC patients." (PMID 38739169, 2024). "Increased LDHB expression is associated with poor survival in many cancers." (PMID 35877003, 2022). "Overall, our findings suggest that AXKO-0046 may be a promising chemical probe to elucidate the role of LDHB-associated pathways in cancer metabolism." (PMID 34725423, 2021). "Moreover, immunohistochemical analysis showed that LDHB was primarily localized in cancer-associated adipocytes, especially where adipocytes are in direct contact with cancer cells." (PMID 33353120, 2020). "Downregulation of drs may contribute to the enhanced glycolysis via increased LDHB expression, which is closely associated with malignant progression of cancer cells." (PMID 26918353, 2016). "Thus, our results confirm our hypothesis that LDHB suppresses ferroptosis, particularly mitochondria-associated ferroptosis, in cancer cells." (PMID 40090955, 2025). "Thus, it will be interesting to explore whether expression profiles linked to the tissue of origin or genetic alterations associated with cancer could serve as markers for sensitivity to LDHB silencing." (PMID 40790017, 2025). "In contrast, the biological roles and regulatory mechanisms of LDHB in cancer are relatively underexplored and poorly understood." (PMID 40733189, 2025). "LDHB is a participant in the lysosomal activity and autophagy of cancer cells, and participates in the process of self-promotion of tumorigenicity and the development of drug resistance in cancer cells." (PMID 40565047, 2025). "In summary, our study revealed that silencing LDHB results in mitochondrial lipid peroxidation in a wide range of cancer cells, corroborating previous findings by others and our own that LDHB is mainly localized in mitochondria." (PMID 40090955, 2025). "Nevertheless, this experimental approach will enable the exploration of LDHB’s potential as a therapeutic target and prognostic biomarker for cancer immunotherapy." (PMID 40790017, 2025). "The relationship between LDHB expression and cancer is complex: LDHB is silenced by promoter methylation in several cancers, but increased LDHB expression has been described in several adenocarcinomas, including NSCLC (see8 for references)." (PMID 40158058, 2025). "Lactate dehydrogenase B (LDHB) is a glycolytic enzyme that promotes lysosomal acidification and autophagy in cancer cells." (PMID 39979670, 2025). "Further, combined RT and short-term LDHB silencing consistently reduced fractional survival in all twelve tested cancer cell lines from different genetic backgrounds and tissues of origin." (PMID 40090955, 2025). "We further showed that the anti-ferroptotic function of LDHB can be exploited to sensitize cancer cells to radiotherapy, a known inducer of ferroptosis." (PMID 40090955, 2025). "For example, lactate dehydrogenase B (LDHB) is highly expressed in cancer cells and catalyzes lactate metabolism to control lysosomal acidification and vesicle maturation." (PMID 39893499, 2025).
cancer (continued). "Lactate dehydrogenase B (LDHB) fuels oxidative cancer cell metabolism by converting lactate to pyruvate." (PMID 40090955, 2025). "It has been reported that the selective knockdown of LDHB in breast cancer significantly reduces the proliferation of cancer cells in vitro and in vivo." (PMID 40565047, 2025). "Intriguingly, the expression of GPD2 (and also AIFM2, which encodes FSP1) showed a mutually exclusive expression pattern, whereas DHODH showed a positive correlation with LDHB in a large collection of cancer cell lines." (PMID 40090955, 2025). "Studies have confirmed that LDHB can be silenced by methylation in some cancers, whereas LDHB is also highly expressed in other cancers." (PMID 38764020, 2024). "Numerous studies have confirmed the upregulation of LDHA expression in cancer cells, whereas the expression level of LDHB remains relatively unchanged in cancer cells and normal tissues." (PMID 38731521, 2024). "LDHB is silenced by promoter methylation in several cancer types, yet overexpressed in most other cancers." (PMID 39213172, 2024). "Lactate dehydrogenase A (LDHA) and LDHB are lactate dehydrogenase tetrameric enzymes utilized by cancer cells to produce lactate from pyruvate." (PMID 38956544, 2024). "Literature has also revealed interactions between Aurora-A and LDHB, regulating LDHB phosphorylation to enhance the conversion of pyruvate to lactate, thereby promoting the Warburg effect and mediating cancer progression." (PMID 38952967, 2024). "The expression and prognosis of LDHB in cancer are controversial, and the clinical value of LDHB in ccRCC is unclear." (PMID 37547725, 2023). "For cancer basal in dataset 1, we identified 336 genes highly expressed and presenting high stemness scores, among the top expressed genes with high stemness is LDHB, which has a known role in cancer cell proliferation." (PMID 38017371, 2023). "Silencing LDHB selectively inhibited basal autophagy and cell proliferation in cancer cells and induced cell death." (PMID 37333985, 2023). "In the cancer cell, LDHB catalyzes the transformation of lactate and NAD (+) to pyruvate, NADH, and H (+) more than in normal tissue." (PMID 36980995, 2023). "Studies showed LDHA and LDHB both function redundantly in cancer, so targeting both would be more advantageous for therapeutic purposes, In melanoma, cas9-mediated deletion of both isoenzymes showed favorable effects on tumor mass shrinkage." (PMID 37762231, 2023). "The central carbon metabolism in cancer pathway (ecb05230, e.g., LDHB, HK2) controls cancer metabolic adaptations through aerobic glycolysis, elevated glutaminolysis, dysregulated tricarboxylic acid cycle and pentose phosphate pathways." (PMID 36553455, 2022). "The relationship between LDHB expression and cancer is complex: LDHB is silenced by promoter methylation in several cancers, but increased LDHB expression has been described in several adenocarcinomas, including NSCLC." (PMID 35877003, 2022). "The authors suggest that LDHB is a potential treatment target in cancers characterized by aberrant activation of the mTOR signaling cascade." (PMID 36551514, 2022). "Another post-translational modification of LDHB that affects its activity is serine 162 phosphorylation by Aurora-A, a serine/threonine kinase overexpressed in cancer." (PMID 36551514, 2022). "Even though four putative acetylation sites were identified in LDHB by mass spectrometry, only K329 has been identified as functional in cancers." (PMID 36407005, 2022). "On the contrary, LDHB expression in cancer cell lines was 2–7 times higher than that in Met5A cells, except in H2452 cells that had larger variability." (PMID 36304150, 2022). "LDHB is essential in the stromal-metabolic reprogrammed TME mediated by cancer, and it serves as the foundation for the stromal-epithelial metabolic coupling pathway." (PMID 35646923, 2022).
cancer (continued). "The influxed lactate is converted to pyruvate with the help of LDHB present in CAFs, which is then used as a valuable fuel for the function of CAFs and also utilized by cancer cells by a reciprocally-supportive metabolic relationship." (PMID 35646923, 2022). "Our work identified LDHB as a novel regulator of telomerase activity which is required for telomere length maintenance and prevents cancer cells from senescence." (PMID 35669414, 2022). "A previous study revealed that LDHB is a key contributor to lysosomal activity and autophagy in both oxidative cancer cells and glycolytic cancer cells through regulation of the conversion of NAD+ and NADH." (PMID 35669414, 2022). "Cancer cells with glycolytic and base-like phenotypes were found to have high LDHB expression, whereas LDHB knockdown reduced glycolytic dependence." (PMID 35646923, 2022). "In this perspective, silencing LDHB decreases the cell number in most cancer cell lines in vitro and in vivo." (PMID 36407005, 2022). "This analysis suggests that LDHB silencing reduces the expression of both nuclear and mitochondrial DNA-encoded mitochondrial genes, consistent with the reduced OXPHOS of the cancer cell lines tested." (PMID 35877003, 2022). "Patients with basal-like cancers had high levels of LDHB expression and had a complete pathological response (pCR) to neoadjuvant chemotherapy." (PMID 35646923, 2022). "Following irradiation, the decreased expression levels of LDHA and LDHB in the FaDu cancer cells and the HMC3 microglial cells corresponded to the decreased pyruvate-to-lactate flux on DNP 13C-MRI." (PMID 34436459, 2021). "The metabolic reactions of aerobic glycolysis are catalyzed by enzymes such as HK2, LDHB, and PKM2, which are implicated in cancer." (PMID 33849427, 2021). "In cancer cells, the LDHB enzyme is relatively downregulated in hypoxic conditions; however, its role in hypoxic cancer metabolism has not yet been elucidated." (PMID 33806179, 2021). "Nevertheless, the amount of extracellular lactate and pyruvate remained the same in control and miR-375 decoy cancer cells, suggesting that miR-375-induced LDHB downregulation indeed fosters lactate production in TAMs." (PMID 34158867, 2021). "LDHB promotes autophagy in a variety of cancer cell lines, which can enable advanced solid tumors to recycle intracellular components and alleviate metabolic stress." (PMID 35028610, 2021). "The increased enzymatic activity of LDHB, restoration of the TCA cycle, and suppression of oncogenes via HIF-1α degradation contribute to the loss of malignancy in cancer cells while posing challenges for adaptation to hypoxia." (PMID 33806179, 2021). "A previous study conducted on patients with basal-like cancers reported high expression levels of LDHB." (PMID 34822416, 2021). "After LDHA or LDHB were knocked out, hydrogen peroxide produced by Hela or 4T1 cancer cells were significantly reduced." (PMID 34176927, 2021). "LDHA is a promising target for cancer therapy, whereas LDHB is necessary for basal autophagy and cancer cell proliferation in oxidative and glycolytic cancer cells." (PMID 34725423, 2021). "In the presence of oxygen, cancer cells can oxidize lactate into pyruvate thanks to the lactate dehydrogenase B (LDHB), thus substituting the glucose to fuel the mitochondria." (PMID 33364196, 2020). "The findings indicate that aberrant LDHB expression is cell, stage and cancer type dependent, hence, targeting LHDB expression level would be beneficial diagnostic and therapeutic strategies." (PMID 33053689, 2020). "Under hypoxia, the pyruvate is converted to lactate in cancer cells by lactate dehydrogenase (LDHB)." (PMID 32682359, 2020). "While LDHA is upregulated in variety of cancers, LDHB is specifically upregulated in basal-like TNBC and is an essential gene in TNBC." (PMID 32350346, 2020). "LDHB is silenced by promoter methylation in several cancer types, while in others it is overexpressed or amplified." (PMID 31035592, 2019).